ENTPD2 (ectonucleoside triphosphate diphosphohydrolase 2)
Diseases named in the same sentence as ENTPD2 in open-access papers (continued):
Sharing a sentence is not in itself a finding about the gene and the disease.
colon cancer (continued). "However, additional studies in large patient populations are warranted to further examine the potential of the exosomal ENTPD2 level as a biomarker for patients with colon cancer." (PMID 38755598, 2024). "The serum exosomal ENTPD2 content was substantially elevated in colon cancer patients (P < 0.05)." (PMID 38755598, 2024). "How does ENTPD2 derived from colon cancer cells exert inhibitory effects on CD8+ T cells?" (PMID 38755598, 2024). "Furthermore, we found that ENTPD2 is released primarily in the membrane form into the extracellular space of colon cancer cells via exosomes." (PMID 38755598, 2024). "We revealed that ENTPD2 expression was markedly increased in colon cancer cells." (PMID 38755598, 2024). "Therefore, we investigated the relationship between ENTPD2 expression and immune cell infiltration in colon cancer." (PMID 38755598, 2024). "We conducted preliminary investigations into the presence of ENTPD2 in colon cancer cells, specifically exploring whether ENTPD2 exists in a soluble form or in exosomes in the extracellular space." (PMID 38755598, 2024). "In 23 colon cancer tissues, the ENTPD2 level was higher than those of CD39 and ENTPD8." (PMID 38755598, 2024). "Therefore, we examined whether an abundance of ENTPD2 could be detected within exosomes isolated from colon cancer cells." (PMID 38755598, 2024). "We further selected the MC38 colon cancer cell line derived from C57BL/6 mice and investigated the effects of ENTPD2 on MC38 cells in vivo." (PMID 38755598, 2024). "Among the extracellular ENTPDases (CD39, ENTPD2, ENTPD3 and ENTPD8), ENTPD2 had the highest expression in colon tumor tissues, according to analysis of data in GEPIA2." (PMID 38755598, 2024). "The ATP hydrolysis assay revealed that ENTPD2 knockdown (RKO-shENTPD2 and DLD1-shENTPD2 cells) severely impaired the ability of colon cancer cells to degrade extracellular ATP (P < 0.05)." (PMID 38755598, 2024). "The Cancer Genome Atlas (TCGA) dataset contained data for 514 colon cancer tissues and 41 noncancerous tissues, and in this dataset, ENTPD2 mRNA expression was strongly elevated in human colon cancer tissues (P < 0.05)." (PMID 38755598, 2024). "The ENTPD2 level was significantly higher in colon cancer tissue (n = 85) samples than in noncancerous tissue samples (n = 84) (P < 0.05)." (PMID 38755598, 2024). "In this study, for the first time, we performed a screen and demonstrated that ENTPD2 but not other ATPases (CD39, ENTPD3 and ENTPD8) is highly expressed in human colon cancer cells and is closely associated with poor patient prognosis." (PMID 38755598, 2024). "Here, we found for the first time that ENTPD2 is ubiquitously expressed in colon cancer cells, unlike other ATPases (CD39, ENTPD3 and ENTPD8)." (PMID 38755598, 2024). "Collectively, this evidence indicates that ENTPD2 but not the other ENTPDase family members plays an essential role in colon cancer progression." (PMID 38755598, 2024). "In conclusion, we highlighted critical roles of ENTPD2 in regulating colon cancer that have not been explored before." (PMID 38755598, 2024). "Similarly, ENTPD2 protein expression was significantly greater in 95 colon cancer tissues than in 100 noncancerous tissues in the analysed NCI proteomics dataset (P < 0.05)." (PMID 38755598, 2024). "Collectively, this evidence revealed that ENTPD2 did not directly influence colon cancer cells and that ENTPD2 may promote tumor growth in immunocompetent mice by affecting the tumor microenvironment." (PMID 38755598, 2024). "We found that ENTPD2, rather than the well-known ATPase CD39, is highly expressed in cancer cells and is significantly positively associated with poor patient prognosis in patients with colon cancer." (PMID 38755598, 2024).
colon cancer (continued). "In these sections, we examined the correlation between the level of exosomal ENTPD2 in the serum and the number of tumor-infiltrating CD8+ T cells, as well as the expression level of ENTPD2 in the corresponding tumor tissues, of these 35 patients with colon cancer." (PMID 38755598, 2024). "Similar findings were obtained via TIMER analysis, indicating significant negative correlations between the expression of ENTPD2 and the infiltration of CD8+ T cells, macrophages and neutrophils in colon cancer (P < 0.05)." (PMID 38755598, 2024). "CD8+ T cells are considered the key antitumor effector cells, and we observed a negative correlation between the expression level of ENTPD2 and the number of tumor-infiltrating CD8+ T cells in colon cancer patients and in mouse models." (PMID 38755598, 2024).
endometrial carcinoma (1 paper, 2021). A malignant tumor arising from the epithelium that lines the cavity of the uterine body. "The log rank analysis showed statistically significant differences with a p-value of 0.044, indicating that there was an influence of the ENTPD2 expression in the prognosis of endometrial carcinoma patients." (PMID 33922226, 2021).
experimental autoimmune encephalomyelitis (1 paper, 2017). An autoimmune demyelinating disease of the central nervous system that is produced experimentally in animals by the injection of homogenized brain or spinal cord in Freund's adjuvant. "The present study explores tissue and cellular distribution of ectonucleoside triphosphate diphosphohydrolase 2 (NTPDase2) and the gene and protein expression in rat spinal cord during the course of experimental autoimmune encephalomyelitis (EAE)." (PMID 29163045, 2017).
gastric tumor (1 paper, 2023). "Compared with benign tissues, the CTLA4 and ENTPD2 were highly expressed in gastric tumor tissues, while the AKR1B1, CLDN6, EMB, GPR15 and VWF were highly expressed." (PMID 37066015, 2023).
Obesity (1 paper, 2025). Accumulation of substantial excess body fat. "Although the involvement of ENTPD2 in obesity or metabolic dysregulation remains poorly characterized, the integrative transcriptomic and lipidomic analysis of eWAT identified ENTPD2 as a key DEG potentially involved in adipose tissue regulation." (PMID 41194880, 2025).
sarcoma (1 paper, 2021). A usually aggressive malignant neoplasm of the soft tissue or bone. "ENTPD2, the most stably expressed gene in “A” is a biomarker for lung and hepatocellular carcinomas, while USP31, the most variably expressed gene in “A”, could be a potential target for sarcomas." (PMID 34209090, 2021).
tumor (32 papers, 2014 to 2025). "CCR4, CMA1, ADCY1, RDH12, and ENTPD2 exhibited higher expression levels in the low-risk group, indicating their possible tumor-suppressive functions." (PMID 40243888, 2025). "To examine the potential role of exosomal ENTPD2 in tumor progression, we injected the ExoPD2−high and ExoPD2−low into C57BL/6 mice." (PMID 38755598, 2024). "The overexpression of ENTPD2 in cancer cells augmented tumor progression in immunocompetent mice by inhibiting the function of CD8+ T cells." (PMID 38755598, 2024). "In HCC, MDSCs move to the tumor site via ENTPD2/CD39 L1 signaling under hypoxic conditions where liver CSCs are abundant." (PMID 36207500, 2022). "The hypoxic milieu recruits myeloid-derived suppressor cells (MDSCs) to the primary tumor site by activating the transcription of chemokine ligand in cancer cells and promoting ectonucleoside triphosphate diphosphohydrolase 2 (ENTPD2/CD39L1)." (PMID 33808042, 2021). "Depletion of ENTPD2 can impede tumor growth and strengthen the efficiency of immune checkpoint inhibitors." (PMID 33314730, 2021). "The combination of ENTPD2 inhibitors and immune checkpoint inhibitors significantly increased the infiltration of T cells into the tumor and prolonged survival of tumor-bearing mice, when compared to using immune checkpoint inhibitors alone." (PMID 32316260, 2020). "Co-inoculation of M-MDSCs with ENTPD2 knockdown HCC cells also repressed tumor growth as compared with control HCC cells." (PMID 28894087, 2017). "Concordantly, knockdown of ENTPD2 in mouse HCC cells drastically repressed tumor growth in immune-competent mice." (PMID 28894087, 2017). "To evaluate the effects of ENTPD2 in HCC growth in vivo, we orthotopically inoculated the MHCC97L subclones into BALB/c nude mice and found that knockdown of ENTPD2 drastically reduced tumor growth." (PMID 28894087, 2017). "ENTPD2 promotes tumor progression in vivo by inhibiting the function of CD8+ T cells." (PMID 38755598, 2024). "Interestingly, we found that the level of exosomal ENTPD2 in the serum was consistent with the ENTPD2 expression level within the tumor (r = 0.6736, P < 0.001)." (PMID 38755598, 2024). "To address whether the tumor inhibitory effects of POM-1 are mediated through ENTPD2, we inoculated Entpd1 KO HCC cells into C57BL/6 mice." (PMID 28894087, 2017). "Interestingly, although ENTPD1 and ENTPD2 share similar functions, demonstrated by ENTPD1- and ENTPD2-KO tumor models, ENTPD2 had greater effects on tumor growth, implying that ENTPD2 took the major role in HCC progression." (PMID 28894087, 2017). "Thus, ENTPD2 is harnessed by tumor cells to shun immune‐mediated demolition." (PMID 33314730, 2021). "In the report, it was suggested that HIF-1α may regulate tumor growth by regulating ectoenzyme, ectonucleoside triphosphate diphosphohydrolase 2 (ENTPD2), and extracellular levels of 5′-AMP to promote tumor growth through shaping the microenvironment of the HCC tumor in addition to direct impact." (PMID 29955245, 2018). "ENTPD2 and UCN displayed more restricted expression patterns, primarily in fibroblasts, suggesting their specialized roles in the tumor microenvironment." (PMID 40243888, 2025). "In addition, immunohistochemical staining of C57BL/6 tumor tissues suggested that the quantity of CD8+ T cells in the MC38-ENTPD2 group was significantly lower than that in the MC38-Vector group (P < 0.05); thus, it is rational to hypothesize that ENTPD2 can affect the CD8+ T-cell response." (PMID 38755598, 2024). "Herein, we revealed that ENTPD2 strongly suppressed the production of the cytokines IFN-γ, TNF-α, and Granzyme B by CD8+ T-cell subsets in MC38 tumor tissues." (PMID 38755598, 2024). "The results showed that the expression levels of ADK, ADSL, ATIC, DPYS, ENTPD2, TXNRD1, and UCK2 in at least one tumor cell line were consistent with the predictions." (PMID 37999212, 2023).
tumor (continued). "While ENTPD2 overexpression was a poor predictor of prognosis for HCC, ENTPD2 inhibition was able to slow the progression of the tumor and improve the effectiveness and efficiency of immune checkpoint inhibitors." (PMID 37999212, 2023). "The expression levels of ENTPD2, BARX1, and GFRA3 were higher in LUAD tumor samples than in normal para-tumor samples." (PMID 36353226, 2022). "ITGA8 and ADAMTS8 were downregulated in tumor tissues, whereas FERMT1, CTSV, CPS1, ENTPD2, SERPINB5, and LYPD3 were upregulated in tumor tissues." (PMID 35557945, 2022). "The expression of KHDRBS2 and MYOZ1 was downregulated in the LUAD cancer samples compared with that in the para-tumor normal samples, whereas the expression of BARX1, ENTPD2, and GFRA3 was upregulated in LUAD cancer tissues." (PMID 36353226, 2022). "Compared with ICI monotherapy, the combination of HIF-1-mediated ectoenzyme ENTPD2 inhibitors and ICI (anti-CTLA-4/PD-1) significantly enhanced T cell infiltration into the tumor and extends the survival of tumor-bearing mice." (PMID 33422072, 2021). "AMP is generated via ENTPD2‐mediated hydrolyzation of extracellular ATP and is further hydrolyzed by CD73 to adenosine that stimulates tumor proliferation and metastasis as well as drug resistance." (PMID 33314730, 2021). "Moreover, an increased exosomal ENTPD2 level was correlated with an advanced TNM stage and a high tumor invasion depth (P < 0.05)." (PMID 38755598, 2024). "CD8+ T cells are effector cells in tumor immunity, when MC38 cells were implanted into mice lacking CD8+ T cells using anti-mouse CD8a antibodies, the tumor-promoting effect of exosomal ENTPD2 was eliminated (P < 0.05)." (PMID 38755598, 2024). "Moreover, the results of q-RT PCR showed that CTSV, RGS4, SYT13 and NPTX1 were highly expressed in tumor tissues compared with adjacent tumor tissues, while SLC25A15, ENTPD2 and CA8 were low expressed." (PMID 36684237, 2022). "ENTPD2 transforms extracellular ATP into 5′‐AMP and further suppresses the differentiation of myeloid‐derived suppressor cells (MDSCs), thus facilitating the maintenance of MDSCs and the development of tumor immunosuppressive microenvironment." (PMID 33314730, 2021). "Lastly, we determined the gene hierarchy in the four profiled regions of the tumor, identified the GMR of each region, and analyzed what might be the consequences of overexpressing ENTPD2, the GMR of the primary tumor nodule “A”." (PMID 34209090, 2021). "In summary, our study discloses that hypoxia/HIF-1α induces ENTPD2 in cancer cells to increase the extracellular level of 5′-AMP, which prevents M-MDSCs from maturation, therefore maintaining MDSC undifferentiated in the tumor stroma." (PMID 28894087, 2017). "Furthermore, ENTPD2 expression in both serum exosomes and tissues exhibited a significant negative correlation with the abundance of tumor-infiltrating CD8+ T cells." (PMID 38755598, 2024). "More excitingly, ENTPD2 upregulation was associated with several aggressive HCC clinico-pathological features including presences of direct liver invasion, tumor microsatellite formation and venous invasion, as well as the absence of tumor encapsulation." (PMID 28894087, 2017). "The disparate effects of ENTPD2 on in vitro and in vivo cell growth implied that ENTPD2 might promote tumor growth through shaping the tumor microenvironment rather than having direct impact on tumor cell itself." (PMID 28894087, 2017). "Additionally, we observed a negative correlation between the exosomal ENTPD2 level in the serum of these patients and the number of CD8+ T cells in the corresponding tumor tissue (r =-0.4830, P = 0.0033)." (PMID 38755598, 2024).
cancer (20 papers, 2017 to 2024). A tumor composed of atypical neoplastic, often pleomorphic cells that invade other tissues. "Tissue microarray analysis showed that ENTPD2 was expressed primarily in cancer cells and had a distinctive membrane association." (PMID 38755598, 2024). "Collectively, our findings support the idea that ENTPD2 overexpression accelerates cancer development in C57BL/6 mice via inhibition of CD8+ T-cell function." (PMID 38755598, 2024). "While over-expression of ENTPD2 was a poor prognostic indicator for HCC, ENTPD2 inhibition was able to mitigate cancer growth and enhance the efficiency and efficacy of immune checkpoint inhibitors." (PMID 33858449, 2021). "In HCC, hypoxia induces the expression of ENTPD2 on cancer cells, leading to an increase in extracellular 5′-AMP, which in turn promotes MDSC maintenance by preventing its differentiation." (PMID 34869376, 2021). "The inhibition of ENTPD2 expression can reduce cancer growth and improve the effectiveness of immune checkpoint inhibitors." (PMID 33024640, 2020). "Secondly, HIF-1α induces ectonucleoside triphosphate diphosphohydrolase 2 (ENTPD2/CD39L1) in cancer cells under hypoxia." (PMID 33027968, 2020). "We further find that ENTPD2 inhibition is able to mitigate cancer growth and enhance the efficiency and efficacy of immune checkpoint inhibitors." (PMID 28894087, 2017). "We demonstrated that hypoxia induced ENTPD2 in cancer cells to generate a 5′-AMP-rich microenvironment to keep MDSC undifferentiated." (PMID 28894087, 2017). "Taken together, our study suggests inhibition of ENTPD2 as a promising strategy to increase the efficacy of PD-1/CTLA-4 immune checkpoint inhibitor in cancer treatment." (PMID 28894087, 2017). "In this study, we found that elevated ENTPD2 expression suggests better overall survival, which may be related to cancer type differences and internal heterogeneity of tumors." (PMID 37066015, 2023). "Since ENTPD2 may be a good prognostic marker and therapeutic target for cancer patients, especially for those receiving immune therapy." (PMID 33858449, 2021). "Moreover, M-MDSC differentiation toward mature anti-tumoral monocytes-derived DCs can be achieved using pharmacological inhibitor of ATP-converting ectoenzyme ENTPD2, thus mitigating cancer growth and enhancing the efficiency of immune checkpoint inhibitors." (PMID 31447834, 2019). "Blocking ENTPD2 in cancer cells remarkably restrained HCC growth in vivo." (PMID 28894087, 2017). "Second, we highlight how ENTPD2 is harnessed by cancer cells to escape immune-mediated destruction." (PMID 28894087, 2017). "We hypothesize that blockade of ENTPD2 in cancer cells would impair MDSC maintenance and enhance T-cell penetrance in the tumors, thereby improving the effectiveness of immune checkpoint therapies in cancer treatment." (PMID 28894087, 2017). "Our data suggest that ENTPD2 may be a good prognostic marker and therapeutic target for cancer patients, especially those receiving immune therapy." (PMID 28894087, 2017). "Inhibition of ENTPD2 could suppress the proliferation of cancer cells." (PMID 32903581, 2020). "Intriguingly, our data showed that ENTPD2 but not NT5E was significantly upregulated in HCC, further highlighting the importance of ENTPD2 and 5′-AMP in microenvironment formation and cancer development." (PMID 28894087, 2017). "In concordance with our clinical observation of ENTPD2 overexpression, we further showed that NT5E inhibitor could not prevent the 5′-AMP-induced MDSC maintenance, suggesting that ENTPD2 but not NT5E is critical for MDSC maintenance in the context of cancer." (PMID 28894087, 2017).
ENTPD2 also shares sentences with these, for which no sentence is quoted: esophageal cancer (2 papers); Ileitis (2); infection (2); papillary thyroid carcinoma (2); adenomyosis (1); brain tumors (1); cholangiocarcinoma (1); Cirrhosis (1); endometrial disorder (1); endometrial polyp (1); endometrial tumor (1); endometriosis (1); fibrosis (1); heart failure (1); Hypertension (1); injury (1); ischemia (1); metabolic disease (1); neurodegenerative disease (1); oesophageal cancer (1); ovarian carcinoma (1); virus infection (1).